NOX4 (NADPH oxidase 4)
Diseases named in the same sentence as NOX4 in open-access papers (continued):
Sharing a sentence is not in itself a finding about the gene and the disease.
Hypertension (continued). "Extensive evidence in experimental models of hypertension indicates up-regulation of vascular NOX1, NOX2, and NOX4 as causes of oxidative stress and cardiovascular dysfunction and remodelling." (PMID 34320175, 2022). "Nobiletin also resolved renal damage that was related to modulation of the AT1R/Nox4 cascade in 2K-1C hypertension." (PMID 35662276, 2022). "A previous publication on the role of Nox4 in salt-induced hypertension in Dahl rats suggests that Nox4 has an impact on sodium handling and, thus, total body water content and plasma volume." (PMID 34356336, 2021). "In contrast, in hypertension and kidney injury in a Dahl salt-sensitive (SS) rat model, knockout of Nox4 attenuates blood pressure increase in response to a high salt diet (4%)." (PMID 34356336, 2021). "With respect to NOX4, this isoform is widely expressed, but it appears irrelevant for blood pressure or hypertension and is rather vasoprotective." (PMID 33170835, 2020). "While the contribution of Nox1 and Nox2 homologues to experimental hypertension is well established, the role of Nox4 remains disputed." (PMID 33131726, 2020). "This switch from negative to positive correlation of Rhoa with the ATPases justifies the reported “role of the Nox4-derived ROS-mediated RhoA/Rho kinase pathway in rat hypertension induced by chronic intermittent hypoxia”." (PMID 31979420, 2020). "Studies have shown that NOX2 and NOX4 expression and activity were significantly upregulated under several conditions, including brain ischemia/reperfusion injury, hypertension, hypoxia-related diseases, and DOX-induced cardiomyopathy." (PMID 33273999, 2020). "Treatment of CsA rats with apocynin, catalase, and their combination prevented hypertension and restored renal functional parameters and tissue Nox4 expression in this model." (PMID 32298299, 2020). "In the present study, we confirmed the increases in the expression of Nox1, Nox2 and Nox4 during the development of spontaneous hypertension." (PMID 33131726, 2020). "At early stage of hypertension (3-months) the most pronounced differences were observed in Nox1 and Nox4." (PMID 33131726, 2020). "Increased Nox4 expression is also found in models of Ang II-dependent hypertension including the spontaneously hypertensive rat and the mRen2 rodent model." (PMID 31507536, 2019). "Another study also showed that Ang II induced oxidative stress, hypertension, and cardiac hypertrophy in a renal artery ligation model, mainly via an increase in NOX4 protein abundance." (PMID 31027372, 2019). "Several cardiac NAD(P)H oxidase comprising NOX1, NOX2, and NOX4, appears to be required for the oxidative mechanisms involved in the development of left ventricular hypertrophy in hypertension." (PMID 29156835, 2017). "Recent study suggests the role of certain dominant NOX family such as NOX1, NOX2, and NOX4 in contributing ROS-induced hypertensive LVH." (PMID 29156835, 2017). "ROS generated by NOX4 has been shown to initiate plenty of cardiovascular disorders such as myofibroblast and hypertension." (PMID 29098089, 2017). "On the contrary, activation of peroxisome proliferator–activated receptor γ (PPARγ) with the synthetic ligand rosiglitazone attenuates hypoxia-induced increases in mouse lung NOX4 expression, ROS generation and pulmonary vascular remodeling and hypertension." (PMID 28594389, 2017). "Nox2 promotes the development of endothelial dysfunction, hypertension, and inflammation, and Nox4 protects the vasculature during stress." (PMID 24759683, 2014). "In other hypertension models, higher levels of Nox4 protein (spontaneously hypertensive rat,), or Nox4 mRNA (AngII-infusion, mouse), or both (ren2-rat) were found in the kidney." (PMID 25551569, 2014). "For example, Nox1, Nox2, and Nox4 are increased in several tissues in rats with spontaneous hypertension or angiotensin II-induced hypertension." (PMID 23985827, 2013).
Hypertension (continued). "Hypertension produced an increase in the content of superoxide anions in aortic tissue (p < 0.001) along with increased mRNA levels of the prooxidant enzymes Nox1 (p < 0.01) and Nox4 (p < 0.05)." (PMID 39857381, 2025). "A few genes were upregulated with hypertension (rather than genotype), including some that mapped to GO terms associated with positive regulation of the cytoskeleton (e.g., Nox4 and Alox15)." (PMID 38425784, 2024). "Additionally, NOX2 and NOX4 contribute to functional deficits in the presence of comorbid conditions such as hypertension, obesity, and hyperglycemia." (PMID 39334724, 2024). "Salt-induced hypertension in DSS rats increased H2O2 release by NOX4, and contributed to renal injury by regulating the upstream target of mammalian target of rapamycin complex 1 (mTORC1), increasing immune cell infiltration and proliferation and subsequent renal oxidative stress." (PMID 36829839, 2023). "Moreover, rutin, a flavonol present in CV extracts, has been documented to prevent hypertension and vascular complication by modulating NOX4 and ROS-sensitive NLRP3 inflammasome as a result of its antioxidant and anti-inflammatory action." (PMID 37215635, 2023). "NOX4 was shown to be involved in the development of hypertension in Dahl salt-sensitive (DSS) rats." (PMID 36829839, 2023). "Docetaxel induces hypertension and vascular dysfunction in mice via a Nox4-dependent mechanism." (PMID 35617030, 2022). "The overexpression of Nox4 in endothelial cells reduces hypertension, myocardial inflammation, and fibrosis in response to AngII, whereas the endothelial cell-specific loss of Nox4 exacerbates cardiac hypertrophy, dysfunction, and fibrosis in response to pressure overload." (PMID 36139898, 2022). "However, the relative contribution of Nox4 expression in ECs and SMCs to the pathogenesis of hypertension requires further research." (PMID 34862465, 2021). "We also identified 21 DEGs (e.g., Fn1, Cd34, Plpp3, Tns1, Nox4, and Npnt) that may be involved in the development of hypertension." (PMID 34862465, 2021). "Finally, we investigated the effects of pharmacological inhibition of Nox4 and/or Nox1, on perivascular inflammation and perivascular fibrosis in spontaneous hypertension." (PMID 33131726, 2020). "With the exception of the Nox4 knockout mice, all angiotensin II-treated animals analyzed in the present study, exhibited significant cardiac hypertrophy, which is a usual outcome of hypertension." (PMID 32635630, 2020). "In summary, spontaneous hypertension promotes ageing-associated perivascular inflammation which is exacerbated by Nox4 but not Nox1 pharmacological inhibition." (PMID 33131726, 2020). "Taken together, these findings suggest that while NOX4 has been demonstrated to be involved in the regulation of hypertension, its effects could be cell and disease specific." (PMID 32923955, 2019). "A direct causal role for Noxs in the development of hypertension has been demonstrated in mice lacking Nox1, Nox2, Nox4, or p47phox where Ang II-induced endothelial dysfunction and hypertension are blunted." (PMID 30334629, 2019). "Overexpression of Nox4 in the ECs of transgenic mice leads to vasodilation and decreased blood pressure, suggesting that Nox4 derived ROS could have a protective effect against hypertension." (PMID 28505091, 2017). "A recent report suggests that Nox4 activity could be required for hypertension mediated by chronic intermittent hypoxia, which could be related to the Nox4 increased expression in the kidney." (PMID 28505091, 2017). "Taken together, the increase in Nox1 and Nox4 and the reduction of eNOS expression in 12 week old arteries from SHR could be associated with the maintenance of hypertension." (PMID 25870854, 2015). "Thus, it is likely that the type of experimental hypertension and the location of the blood vessel studied can significantly impact how Nox4 expression is regulated." (PMID 23125837, 2012).
Hypertension (continued). "However, NOX4 remains controversial in the pathologic progression of hypertension." (PMID 39867658, 2024). "Therefore, inhibiting ROS production by targeting Nox4 and Nox1 might provide better antioxidant therapies to prevent the transition from hypertension to chronic heart failure." (PMID 32831633, 2020). "However, in the pathophysiology of hypertension, such as essential hypertension, Nox4 expression seems to be upregulated by the renin-angiotensin system, which may have harmful effects." (PMID 28591344, 2017). "Therefore, NOX4-mediated metabolic remodeling may also be involved in hypertension." (PMID 39867658, 2024). "Further investigation of NADPH oxidase-4/H2O2/mTOR complex 1 (NOX4/H2O2/mTORC1) and PI3K/Akt signaling pathways should be conducted to validate the protective effects of the extract on hypertension-induced renal injury." (PMID 35215280, 2022). "Exercise training attenuated hypertension and renal dysfunction and inhibited the Nx-increased urinary MDA, renal NADPH oxidase, XO activity, and renal expression of Nox2, Nox4, and XO." (PMID 36144240, 2022). "Alterations in ROS production and oxidative stress in hypertension are dependent on activation of vascular NOX1, NOX2, and NOX4, as demonstrated in almost all experimental models." (PMID 34320175, 2022). "Subsequently, we used pharmacological inhibitors of Nox1 (ML171) and Nox1/Nox4 (GKT137831; 60 mg/kg), to modulate NADPH oxidase activity at the early stage of spontaneous hypertension and investigated their effects on perivascular inflammation and fibrosis." (PMID 33131726, 2020). "In animal models of hypertension, cardiac disease and ischemic stroke, Sirt3 has shown to suppress oxidative stress by regulating NOX2, NOX4, SOD2, Nrf2 and FoxO3a." (PMID 30362958, 2018). "Finally, approaches to target Nox4 in other disease settings (e.g. cancer) should take into account the potential cardiac risks that might arise with such an approach, especially in subjects with pressure overload (e.g. hypertension)." (PMID 29040462, 2018). "Angiotensin II, which plays a critical role in the pathogenesis of hypertension, is able to induce the expression of different NOX homologues, including NOX1, NOX2, NOX4, and p22phox." (PMID 29430280, 2017). "Therefore, the relation of Nox4 with hypertension is complex; however, it is tempting to speculate that, depending on its tissue distribution, Nox4 could behave as a protector or inductor of hypertension." (PMID 28505091, 2017). "The oxidative stress is accordingly strengthened in hypertension, verified by the increased expression of NADPH oxidase subtype, including NOX2, NOX4, and p67phox." (PMID 27642495, 2016). "When animals from both functional studies underwent ganglionic blockade, there was a reduced fall in blood pressure in the NOX2 and NOX4 knockdown/knockout mice, indicating that both NOX2 and NOX4 in the PVN contribute to hypertension." (PMID 23717285, 2013). "However, the importance of Nox4 in hypertension remains unclear." (PMID 23125837, 2012). "In our current model of premenopausal hypertension using middle‐aged, ovariectomized rats, E2 impacted neither blood pressure nor vascular Nox4 mRNA, either in normotensive or hypertensive conditions." (PMID 41204447, 2025). "However, recent data has demonstrated endothelial‐derived H2O2 via NOX4, and direct chemical activation of H2O2 induces hypertension." (PMID 41178013, 2025). "On the other hand, under certain conditions, NOX4 has been suggested to be vasoprotective and the increase in VSMC expression, we observed in hypertension may represent a compensatory response to NOX5 up-regulation." (PMID 34320175, 2022). "Our previous studies have proved that activated renin–angiotensin system (RAS) triggers the overproduction of ROS and increases the NAD(P)H oxidase activity and its subunits (NOX2 and NOX4) in the PVN, which produced the excessive ROS during the development of hypertension." (PMID 34899311, 2021).
Hypertension (continued). "As oxidative stress is known to mediate both endothelial dysfunction and vascular stiffness in hypertension, we next investigated vascular superoxide production and Nox2 and Nox4 nicotinamide adenine dinucleotide phosphate oxidases." (PMID 32065054, 2020). "A corresponding study found that mice deficient in NOX4, but not NOX1, are protected from hypertension." (PMID 31239370, 2019). "IgG antibody titers were not correlated with TNF-α, NOX4, renin, and NO in hypertension subjects in any of the models (P>0.05)." (PMID 29752343, 2018). "In both humans with hypertension and in SHR, both local and systemic renin-angiotensin-aldosterone systems are activated, which leads to increased expression of the Nox4 and/or Nox1 proteins and, consequently, to a pro-oxidant state resulting from chronically increased superoxide production 15-17." (PMID 28591344, 2017). "Mechanical stretch upregulated Nox1 and Nox4 expressions but not Nox2, indicating the important role of Nox1 and Nox4 in mechanical stretch/hypertension-induced vascular remodeling." (PMID 26557089, 2015). "As in the case of Eln+/− mice, hypertension of DD mice is related to elevated angII plasma levels, and we have also shown over-expression of several NOX-related genes (Ncf1, Ncf2, Nox2/Cybb and Nox4) and significantly increased oxidative stress in these mice." (PMID 22319452, 2012). "Treatment with inhibitors targeting Nox1, Nox2, and Nox4 (such as apocynin, diphenyl iodide, gp91ds-tat, and GKT137831) in a mouse model of hypertension significantly improved vascular function, normalized blood pressure, and attenuated hypertension-induced cardiac remodeling (Schröder, 2014)." (PMID 39974735, 2025). "Additionally, E2 did not attenuate the ANG‐induced increase in aortic NOX4 expression, suggesting that in this middle‐aged model of menopause E2 is unable to counteract the increase in vascular oxidative stress during hypertension." (PMID 41204447, 2025). "Thus, analyzing the effects of NOX4 in rather inflammatory PVAT might shed further light into its role in dyslipidemia, obesity, endothelial dysfunction and hypertension." (PMID 38790608, 2024). "It is possible that NOX4 along with ROS generated from electron transport chains may act synergistically to enhance oxidative stress in the PVN, contributing to the development of hypertension." (PMID 39594564, 2024). "NOX4 also plays a role in hypertension development at non-physiological, overactive levels." (PMID 37510117, 2023). "Moreover, others have previously shown that TUDCA treatment improved vascular function by reducing ER stress and NOX-2 and NOX-4 expression in mesenteric arteries and aortas in a hypertension and diabetic mouse model (non-pregnant mice)." (PMID 35883766, 2022). "While our study showed that potential adverse effects of Nox4/Nox1 pharmacological inhibition are pronounced in the vasculature in hypertension, the current study did not establish a clear answer to the problem of the relationship between perivascular inflammation and BP elevation in SHR." (PMID 33131726, 2020). "However, the role of Nox1 and Nox4 in the context of ageing, development of spontaneous hypertension and in modulation of the perivascular inflammation has not been investigated to date." (PMID 33131726, 2020). "A role for NOX4 in hypertension is contentious and has not yet been conclusively determined." (PMID 32923955, 2019). "Thus, we may suggest that the increased transcription of Nox4 in the renal medulla of ISIAH rats may contribute to increased rate of ROS production and hypertension development." (PMID 28105926, 2016). "However, the role of Nox4 in hypertension is not entirely clear because Nox4 knockout mice are normotensive." (PMID 23985827, 2013).
Hypertension (continued). "However, that vascular dysfunction and increased agonist-induced contraction in aorta, and increased myogenic tone in mesenteric artery was not reversed by Tempol in vivo makes it unlikely that Nox4 mediates the vascular dysfunction or hypertension observed in S-P467L mice." (PMID 25122005, 2014). "Expression of VSMC NOX4, but not NOX1 or NOX2, was also increased in hypertension." (PMID 34320175, 2022). "Unlike NOX4, NOX5 produces superoxide, which can either uncouple endothelial NOS in hypertension by oxidation of H4Bip in a sepiapterin-reversible manner or scavenge NO to form peroxynitrite, which may also act as a cytotoxic agent or vasodilator." (PMID 33170835, 2020). "Furthermore, we observed that the increase in PDI is accompanied by an increase in Nox1, but not Nox4, expression and that PDI plays a role in Ang II-induced redox signaling in hypertension." (PMID 25870854, 2015).